CAST (calpastatin)
Diseases named in the same sentence as CAST in open-access papers (continued):
Sharing a sentence is not in itself a finding about the gene and the disease.
tumor (27 papers, 2001 to 2026). "The analysis of calpastatin immunostaining proved a significant loss of expression in tumor ECs compared to normal vessels." (PMID 39156707, 2024). "We further developed a CAST platform equipped with a PLK1-specific ASO to logically regulate PLK1 gene expression which is highly associated with tumor cell proliferation, to verify CAST effectiveness." (PMID 37580346, 2023). "Six have been indirectly linked to tumour malignancy and are thus new splicing targets to study (CAST, CSF1, PLOD2, SLK, SPAG9, TSC2)." (PMID 33845831, 2021). "High expression of calpastatin was associated with ER positive tumours (χ2=5.720, d.f.=1, P=0.017) and high calpain-1 expression was associated with PgR positive tumours (χ2=5.457, d.f.=1, P=0.019)." (PMID 27323818, 2016). "The calpain system, including the proteolytic enzymes μ-calpain and m-calpain and their endogenous inhibitor calpastatin, has been implicated in cancer progression and response to therapy in a limited number of studies and tumour types." (PMID 22435971, 2012). "The calpain system, including calpastatin, is implicated in tumour progression through its role in multiple cell pathways including cellular migration, apoptosis and cell survival." (PMID 23140395, 2012). "The left tibialis anterior muscle of mice bearing the C26 tumor was transfected with an expression vector encoding a calpastatin species containing, in addition to a single inhibitory unit, also the regulatory L-domain (RNCAST600; transfection efficiency: 30%)." (PMID 28469577, 2017). "In addition to the association with survival of these patients, high calpastatin expression is associated with ER positive tumours and high calpain-1 expression is associated with PgR positive tumours." (PMID 27323818, 2016). "In the bile duct and ampulla carcinoma cohort a significant association was observed between high cytoplasmic calpastatin expression and patients aged above 60 years and high nuclear calpastatin expression and increased tumour stage and the presence of vascular invasion." (PMID 23140395, 2012). "In addition an association between high nuclear calpastatin expression and increased tumour stage (χ2=9.303, d.f.=3, P=0.026) and the presence of vascular invasion (χ2=4.093, d.f.=1, P=0.043)." (PMID 23140395, 2012). "Functional studies revealed that CAST exhibits tumor-promoting activity in both MDA-MB-231 and HCC-1954 cells." (PMID 40175348, 2025). "CAST, a metal ion transition gene, and corresponding proteins such as calpain have been identified as positive factors in tumorigenesis and tumor progression in GC." (PMID 34510798, 2021). "The expression levels of calpain and calpastatin have been described in a number of tumour types, including pancreatic, ovarian and gastro-oesophageal." (PMID 27323818, 2016). "To determine the respective importance of each target, we overexpressed calpastatin in tumor and/or host in isolation." (PMID 23565252, 2013). "The development of highly specific calpain inhibitors with potential medical applications in cancer should take into account the opposing roles of the calpain/calpastatin system in initial tumor growth and subsequent metastatic dissemination." (PMID 23565252, 2013). "Decreased levels of both calpastatin and 130 kDa Ca2+-ATPase have been also detected in the heart of the tumour-bearers." (PMID 11286475, 2001). "Since CAST has tumor-promoting activity, we hypothesized that CAST upregulation in TXNIP-OE HCC-1954 cells might explain the late-onset acceleration in the growth of TXNIP-OE HCC-1954 tumors in NSG mice." (PMID 40175348, 2025). "Taken together, these results suggest that CAST plays a tumor-promoting role in MDA-MB-231 cells." (PMID 40175348, 2025). "Consistent with these in vitro results, CAST-KD MDA-MB-231 tumors in NSG mice exhibited reduced tumor volume and weight relative to WT MDA-MB-231 tumors, whereas CAST-OE MDA-MB-231 tumors displayed greater tumor volume and weight relative to WT MDA-MB-231 tumors." (PMID 40175348, 2025).
tumor (continued). "Since CAST exhibited a tumor-promoting function in MDA-MB-231 cells, we investigated whether CAST plays a similar role in HCC-1954 cells." (PMID 40175348, 2025). "Together, these results could also partly explain the tumor-promoting function of CAST, which was upregulated in TXNIP-OE HCC-1954 cells, by counteracting the tumor suppressor activity of TXNIP." (PMID 40175348, 2025). "Taken together, these findings further establish CAST’s tumor-promoting activity." (PMID 40175348, 2025). "Given CAST’s role as a tumor promoter, the elevated CAST levels in TXNIP-OE HCC-1954 cells may counteract TXNIP’s antitumor effects." (PMID 40175348, 2025). "Moreover, PAAD tumours were insensitive to Erlotinib, Sunitinib and Imatinib in the high mitophagy subtype and high CAST, CCDC6, and ERLIN1 expressed subtypes." (PMID 35938160, 2022). "Surprisingly, whereas in murine experimental models of cancer, tumor size usually correlates to metastatic dissemination, we observed a discrepancy between the slow tumor growth and the high rate of metastatic dissemination in calpastatin transgenic tumors." (PMID 23565252, 2013). "Since IL-17 and Th17 pathway seem to exert anti-tumor properties, it could be hypothesized that immune cells overexpressing calpastatin have reduced ability to limit tumor cell viability and metastatic dissemination." (PMID 23565252, 2013). "To further define the mechanisms whereby the calpain/calpastatin system would modify tumor size and metastatic properties, we studied in vitro the influence of calpastatin transgene expression on cell proliferation, spontaneous or induced apoptosis, and migration." (PMID 23565252, 2013). "The design of our studies allows (i) to specifically inhibit calpain activity using calpastatin and (ii) for the first time, to discriminate the roles of the calpain/calpastatin system in tumor cells (growth, death, migration) and in host (angiogenesis, immune response)." (PMID 23565252, 2013). "Main studies report that calpains increase while calpastatin limits tumor dissemination." (PMID 23565252, 2013). "After tumour transplantation, total calpastatin activity progressively declined, while total calpain activity remained unchanged, resulting in a progressively increasing unbalance in the calpain/calpastatin ratio." (PMID 11286475, 2001). "Additionally, using WGCNA and machine learning, three diagnostic gene signatures (CAST, CCDC6, and ERLIN1) for the high level mitophagy subtype were obtained, which were closely associated with tumour immune microenvironment and chemotherapy sensitivity in PAAD." (PMID 35938160, 2022). "Consistent with the initial inhibitory events, knocking down CAST in TXNIP-OE HCC-1954 cells led to a significant reduction in cell proliferation, colony formation, and tumor growth in a mouse xenograft model." (PMID 40175348, 2025). "Relative to WT HCC-1954 cells, CAST-OE HCC-1954 cells also demonstrated accelerated tumor growth in NSG mice, as evidenced by greater tumor volumes and weights." (PMID 40175348, 2025). "This Cas13a-TAT-crRNA complex (CAST-crRNAa) demonstrated enhanced cellular uptake and reduced PDL1 expression in tumor cells." (PMID 39128990, 2024). "Though CAST has been discovered to have a prominent impact on GC patients’ survival, after multivariate adjustments, multi-database datasets revealed that macrophages might play a key role in immune regulation in the GC microenvironment, promoting tumor suppression." (PMID 35625600, 2022). "Many of the hub AS events, including AS events in KIFB1, SEC31A, CAST and CLSTN1, were up‐regulated in invasive and diffuse GC tissues and were significantly related to extracellular matrix and tumour stromal score." (PMID 32939931, 2020). "Furthermore, expression of four proteins is associated with tumor progression/high risk AML: DOT1L, mTOR, VIM and ZNF521, whereas the expression of six proteins is associated with tumor suppression/low risk AML: AEBP2, CAST, CBFB, LSP1, MAP1S and probably PCBP1." (PMID 30634713, 2019).
tumor (continued). "Compared to wild-type C57BL/6J-Tg(TRAMP)824Ng/J males, TRAMP x CAST/EiJ, TRAMP x NOD/ShiLtJ and TRAMP x NZO/HlLtJ F1 males displayed significant increases in tumor growth." (PMID 23620793, 2013). "It remains unclear whether enhanced calpain kinase activity contributed directly to reduced CAST-KD_TXNIP-OE HCC-1954 cell proliferation and tumor growth." (PMID 40175348, 2025). "Overexpression of CAST, an endogenous inhibitor of calpains, significantly increased xenograft tumor growth for both MDA-MB-231 and HCC-1954 cells, underscoring its novel role as a tumor promoter." (PMID 40175348, 2025). "In human GBM, the transcriptomic data elaborated from the TCGA and GTEx gene expression datasets show that calpain and calpastatin are upregulated in GBM tissues compared to normal brain tissue, likely suggesting a role of the calp/cast system in tumor development and aggressiveness." (PMID 39139809, 2024). "In these three subjects, the negative-mutation status of the tumor for the specific mutation detected in the NLP was confirmed using highly sensitive and specific TaqMan PCR (CAST-PCR)." (PMID 34257550, 2021). "When administered intravesically, the interaction with FCS facilitates transepithelial delivery of CAST-crRNAa, rearranging tight junction proteins in bladder epithelium and enabling TAT-mediated cellular internalization and PDL1 expression regulation in tumor tissues." (PMID 39128990, 2024). "Furthermore, the mRNA expression of CAST, CCDC6 and ERLIN1 could potentially predict the tumour’s sensitivity to Erlotinib, Sunitinib and Imatinib." (PMID 35938160, 2022).
cancer (22 papers, 2012 to 2025). A tumor composed of atypical neoplastic, often pleomorphic cells that invade other tissues. "Altered regulation of the calpastatin-calpain proteolytic system is associated with several pathological disorders, including cancer." (PMID 29581866, 2018). "CAST is an endogenous inhibitor of calpains (m-calpain and μ-calpain) but its involvement in cancer biology remains poorly understood." (PMID 40175348, 2025). "Further research into the interactions between TXNIP, CAST, and IL-24 is essential to better understand their roles in cancer." (PMID 40175348, 2025). "Lastly, the complex roles of CAST and IL-24 in cancer underscore the need for more comprehensive studies to fully understand the diverse effects and therapeutic potential of these molecules." (PMID 40175348, 2025). "The calpain/calpastatin (calp/cast) proteolytic system is involved in critical physiological processes and cancer progression." (PMID 39139809, 2024). "CAST expression and pan-cancer surveyance were analyzed using the Human Protein Atlas (HPA) and Gene Expression Profiling Interactive Analysis 2 (GEPIA2) database." (PMID 35625600, 2022). "We also showed that casein kinase 2, a pro-survival kinase overexpressed in many cancer types, phosphorylated calpastatin at Ser-633." (PMID 29581866, 2018). "Calpastatin levels, however, vary across cancer types as the protein is reported to have high expression in endometrial cancer and low expression in rhabdomyosarcoma." (PMID 29581866, 2018). "While calpain‐1 and calpastatin levels varied widely in the cancer cell lines we examined in this study, calpain‐2 levels were consistently detected and showed interesting patterns of low, moderate, and high expression." (PMID 29210197, 2018). "Overall, our results evidence that studies of the calpain/calpastatin in cancer models should distinguish the role of calpains in tumoral cells and in host tissues/immune system." (PMID 23565252, 2013). "However, future studies are needed to determine if calpastatin contributes to radiation resistance in other cancers as well." (PMID 29581866, 2018). "However, the exact role of CAST related to cancer susceptibility or DNA repair has not been elucidated yet." (PMID 23593158, 2013). "Calpastatin (CAST) is involved in many important physiological processes, including cell cycle, ECM, cancer cell proliferation, metastasis, and apoptosis." (PMID 35265613, 2022). "(A) Kaplan-Meier plot of the survival of male mice in which cancer was observed during gross necropsy (N = 38 male mice; WT Sham 5, L-RKO Sham 9, WT CAST 10, L-RKO CAST 14)." (PMID 32720643, 2020). "The highest up-regulated lncRNA was lnc-MMP10-3 (absolute FC = 1469.95) among ESCC tissues versus paired non-carcinoma tissues and a total of 809 genes (e.g. S100A16, OLFML2B, and CAST) were related to lnc-MMP10-3 as the standard of absolute PCCs value > 0.8." (PMID 31235759, 2019). "Despite a clear involvement of the calpastatin-calpain system in cancer, its contribution to treatment resistance has not yet been explored." (PMID 29581866, 2018). "Our results indicate that calpastatin phosphorylation promotes radiation resistance in GBM cells by increasing the activity of calpain proteases, which are known to promote survival and invasion in cancer." (PMID 29581866, 2018). "The lack of effect of RNCAST600 in preventing cancer-induced muscle wasting could depend on a sort of “calpastatin resistance”." (PMID 28469577, 2017). "Future challenges will be to explore whether the transfection of different forms of calpastatin (i.e., without L-domain or with an L-domain lacking exon 6) could affect cancer-induced muscle wasting." (PMID 28469577, 2017).
infection (18 papers, 2008 to 2025). The state of being infected such as from the introduction of a foreign agent such as serum, vaccine, antigenic substance or organism. "Infection of the CAST and PWK mice led to rapid weight loss which was more profound and longer lasting for CAST." (PMID 39149485, 2024). "Recent studies have shown that infection of host cells with Mycoplasma hyorhinis caused inhibition of calpain activity through upregulation of its inhibitor, calpastatin." (PMID 21507248, 2011). "In contrast, PWK mice, which lost significant weight and displayed some susceptibility to the infection, had statistically significant (p < 0.0001) reduced levels of the virus in the lungs (2.84 ± 0.19 log10PFU, day 3 post-infection) compared to K18-hACE2 and CAST mice." (PMID 39149485, 2024). "This is supported by studies in CAST/EiJ mice, which showed that infection with clade IIb triggered a faster and more robust immune response than clade IIa, resulting in less severe disease." (PMID 41476947, 2025). "CAST mice displayed the highest levels of bronchiolar necrosis throughout all 5 days of infection analyzed." (PMID 39149485, 2024). "Ultimately, all female and nearly all male CAST mice succumbed to infection with Beta VOC by either 5- or 7-days post infection for females and males, respectively." (PMID 39149485, 2024). "The cytokine signatures of CAST and K18-hACE2 mice show sustained increases at 3- and 5- days post-infection for a number of known pro-inflammatory chemokines and cytokines." (PMID 39149485, 2024). "We showed that TNF-α induced β-catenin and suppressed IκB expression in HUVECs, and these effects were both attenuated by infection with Ad-CAST." (PMID 32665543, 2020). "TNF-α promoted the proliferation, migration, and tube formation in HUVECs, but these effects were attenuated by infection with Ad-CAST." (PMID 32665543, 2020). "DCQ analysis of the lung transcriptome showed equal numbers of monocytes and macrophages in CAST/EiJ and 129S1/SvlmJ mice and a much stronger reduction in dendritic cells in CAST/EiJ compared to 129S1/SvlmJ mice after infection." (PMID 26921172, 2016). "In summary, the amount of granulocytes in the blood of CAST/EiJ mice increased after infection which suggests a normal primary signaling of infected cells to the hematopoietic system and the release of leukocytes into the blood." (PMID 26921172, 2016). "In summary, CAST/EiJ mice exhibited in general much lower numbers of immune cells in the lungs before and after infection." (PMID 26921172, 2016). "For example, highly susceptible strains (C57BL/6J, 129S1/SvlmJ, CAST/EiJ) exhibited a strong increase in IFIT3 and IFIT44 expression after infection but only a relatively low increase in expression was observed in the resistant strain PWK/PhJ." (PMID 27193691, 2016). "Another example was the Tdrd3 gene, which showed differential isoform expression in CAST/EiJ mice on day 2 after MA15 infection." (PMID 24902603, 2014). "To investigate the role of calpain in ROS production, we over-expressed calpastatin in HUVECs by infection with Ad-CAST and then incubated these cells with normal (5 mmol/L) or high glucose (30 mmol/L) for 48 hours." (PMID 24886224, 2014). "Control cells and calpastatin- or calpain-overexpressing NIH-3T3 cells (infection efficiencies were >95%) were stimulated with LPS or IL-17, and the IL-6 concentration in the culture supernatants was measured by ELISA." (PMID 22046434, 2011). "Remarkably, infection of old VSMC with an adenovirus harboring CAST indeed inhibits calpain-1 activity and generates a pattern of proteolytic products of vimentin resembling that from the untreated young cells (30 mo)." (PMID 18493299, 2008). "Notably, RT-qPCR analyses revealed a consistent increase in lnc-CAST expression at 24 h-post-infection (hpi) compared to the control." (PMID 38715098, 2024).